BCL2 (BCL2 apoptosis regulator)
Diseases named in the same sentence as BCL2 in open-access papers (continued):
Sharing a sentence is not in itself a finding about the gene and the disease.
leukemia (continued). "Insofar as this effect can be partially rescued by ectopic BCL2 overexpression, this indicates that MYB-induced dysregulation of BCL2 expression is required for MYBMIM-induced anti-leukemia effects." (PMID 29317678, 2018). "Coexpression of Bcl-2 and P-gp confers resistance against induction of apoptosis in leukemia cells originated from alteration in lymphoid pathway of hematopoiesis." (PMID 29723984, 2018). "Hsa-mir-16 ranked 3rd, its expression was inversely correlated with Bcl2 expression in leukaemia, and both microRNAs negatively regulate B cell lymphoma 2 (Bcl2) at a posttranscriptional level." (PMID 29665774, 2018). "For example, the antifungal drug ciclopirox was predicted to inhibit B-cell lymphoma 2 (BCL-2) as a treatment for leukemia." (PMID 29317676, 2018). "We found that MYBMIM downregulated the MYB-bound BCL2 enhancer, leading to downregulation of BCL2 expression and apoptosis of leukemia cells." (PMID 29317678, 2018). "β-Sitosterol can also induce apoptosis of human leukemia cell line U937 by activating caspase-3 protease and regulating Bax/Bcl-2 ratio." (PMID 30670974, 2018). "MC2884 induced massive apoptosis in ex vivo human primary leukemia blasts with poor prognosis in vivo, by targeting BCL2 expression." (PMID 29876013, 2018). "Recently, the FDA approved the use of venetoclax, a specific BCL-2 inhibitor that has strong inhibitory activity in multiple types of leukemia." (PMID 29854301, 2018). "We previously developed cell‐penetrating VDAC1‐derived peptides that interact with hexokinase (HK), Bcl‐2, and Bcl‐xL to prevent the anti‐apoptotic activities of these proteins and induce cancer cell death, with a focus on leukemia and glioblastoma." (PMID 29698587, 2018). "Expression of Bcl-2 mRNA was generally higher in leukemia samples than in the control group (p < 0.05)." (PMID 29515335, 2018). "In the first decade following this shift, great progress was made targeting BCL-2 in a variety of leukemias, ranging from CLL to LAML." (PMID 30158527, 2018). "This indicates BCL-2 overexpression is relatively common in leukemia, highlighting the importance of better understanding all aspects of BCL-2 gene regulation." (PMID 27856324, 2017). "Cell death in leukemia cells as result of kaempferol treatment is accompanied by decreasing the expression of Bcl-2 and increasing the expressions of Bax." (PMID 28587155, 2017). "Bfl-1 expression can also counteract the effects of inhibitors of other anti-apoptotic family members (e.g. Mcl-1, Bcl-2) in leukemia and lymphoma." (PMID 28594323, 2017). "Further work in xenograft models confirms not only the enhanced sensitivity of MLL-r leukemias to BCL-2 inhibition compared to other subgroups of ALL but also the enhanced efficacy of combined inhibition of BCL-2 and BCL-XL." (PMID 28232907, 2017). "Because only Bcl-2 Tg Eμ-Tcl1 Tg leukemias were completely refractory to PI3Kδi-induced cytotoxicity in vitro, additional BH3-only proteins likely contribute." (PMID 27843137, 2017). "Past work has suggested that MLL-AF4 leukemias are particularly sensitive to loss of BCL-2 activity, and we were able to extend this observation by illustrating that BCL-2 is a key therapeutic target in MLL-AF4 leukemias." (PMID 27856324, 2017). "As a well-established inhibitor of mitochondrial apoptotic pathways, BCL2 has emerged as a potential therapeutic target in leukemias." (PMID 27008505, 2016).
leukemia (continued). "B-cell lymphoma 2 (BCL2), a well-established inhibitor of mitochondrial apoptotic pathways, has emerged as a potential therapeutic target in both leukemia and solid tumors." (PMID 27008505, 2016). "X. Wang and Y. Wang indicated that Rh2 significantly prolonged the survival of mice with pediatric leukemia and induced apoptosis of leukemia cells through miR-21-modulated suppression of Bcl-2." (PMID 27446225, 2016). "Bcl-2-induced ROS production in leukemia cells is accompanied by increases in cellular oxygen consumption, cytochrome c oxidase (COX)/complex-IV activity, and mitochondrial respiration." (PMID 26621844, 2016). "Despite the survival delay, even mice bearing re-programmed BCL-2-dependent p185+ B-ALL cells that were treated with venetoclax for a 5 day window eventually developed a fatal leukemia." (PMID 26862853, 2016). "MLL-r leukemia cells that were resistant to the compound were characterised by significantly higher baseline gene expression levels of MEIS1 and BCL2 in comparison to CCI-007 sensitive MLL-r leukemia cells." (PMID 27317766, 2016). "Vitexin is suggested to serve as a therapeutic agent for the treatment of human leukemia, as it promoted the expression of cleaved caspase-3 and cleaved caspase-9 in leukemia cells and simultaneously reduced Bcl-2 expression and therefore induced apoptosis." (PMID 27630565, 2016). "Overexpression of Bcl-2 in leukemia cells increases the overall rate of mitochondrial respiration and ROS production, accompanied by an increase in the localization of the Va and Vb subunits of COX in mitochondria and subsequent enhancement of COX activity." (PMID 26621844, 2016). "Further studies suggested that zephycandidine A induces apoptosis in leukemia cells by the activation of caspase-3, upregulation of Bax, downregulation of Bcl-2, and degradation of PARP expression." (PMID 27658482, 2016). "In fact, the overexpression of the antiapoptotic gene BCL2 in leukemia cells overexpressing the protein CD20 has been evidenced in patients affected by leukemia." (PMID 28335259, 2016). "Cimmino etal. found that miR-15a and miR-16-1 suppress the expression of Bcl-2 resulting in the induction of apoptosis in leukemia cell lines." (PMID 26494988, 2015). "show that MLL leukemias are highly sensitive to BCL-2 inhibitors, especially when combined with drugs that target mutant MLL complex activity." (PMID 26711339, 2015). "Leukemia types in which Bcl-2 is overexpressed have a poor prognosis and they have traditionally been related to chemoresistance, emphasizing the importance of this finding." (PMID 26688757, 2015). "Crossing of these fish with zebrafish overexpressing the bcl2 gene dramatically accelerated the onset of leukemia, indicating a strong cooperation between the NOTCH1 and BCL2 pathways." (PMID 25884214, 2015). "This led to the finding that the DOT1L inhibitors sensitize MLLr leukemias to BCL-2 inhibition with ABT-199." (PMID 26711339, 2015). "For example, anthocyanin, a member of the flavonoid family, induces apoptosis of leukemia U937 cells by down-regulating Bcl-2 expression." (PMID 26672745, 2015). "For the triterpenoid CDDO-Me it was demonstrated that it is able to suppress NF-κB and NF-κB-dependent gene products that mediate cell survival, including survivin, Bcl-2 and cIAP2 in human leukaemia and ovarian cancer cells." (PMID 26244918, 2015). "The styryl-lactone Chel A has been shown to trigger apoptosis in human promyelocytic leukemia HL-60 cells by downregulating Bcl-2 expression, thereby exhibiting the potential as a chemotherapeutic agent in treating human leukemia cells." (PMID 24553354, 2014). "Previously, we have also shown that a heptamer type of 2′-O-methylated sgRNA, mh1(Bcl-2), which targets human Bcl-2 mRNA, can be taken up by cells without any transfection reagents and that it can induce apoptosis of leukemia cells." (PMID 25437003, 2014).
leukemia (continued). "This gene set, which includes several critical regulators of myelopoiesis and leukemia including BCL2, C-MYC and IRF8, was also downregulated in other AML cell lines sensitive to I-BET." (PMID 24220271, 2014). "Thus, Bcl-2 proteins may play an important role in the proliferation of MLL-associated leukemia." (PMID 25285531, 2014). "Bcl-2 is constitutively activated in leukemia cells, thus creating a block in cancer cell apoptosis, which develop resistance in cells." (PMID 25383546, 2014). "Suggesting that Mcl-1 and Bcl-2 also regulated by miR-29a and miR-29b at post-transcriptional level and both of them contribute to the blocked apoptosis of leukemia cells in CML." (PMID 25006537, 2014). "It is of utmost importance to elucidate the precise molecular events that connect Bcl-2, apoptosis, and electron transport in leukemia cells in order to develop effective therapies to eradicate the elusive LSC." (PMID 23565503, 2013). "Co-treatment with D,L-methadone and an anti-Bcl-2-agent leads to synergistic effects in leukemia cells." (PMID 23633472, 2013). "BCL2 down-regulation was previously observed with the BET inhibitor I-BET151, which displaced BET proteins from the BCL2 transcriptional start site in MLL-fusion leukemia cell lines." (PMID 24009722, 2013). "The susceptibility in U937 leukemia cells to apoptosis induced by PTX and MG132, it can explain for the decrease in the expression of Bcl-2 and Bcl-XL proteins when the cells are expose to both drugs." (PMID 23445492, 2013). "One example is ABT-737, a BH3 mimetic that inhibits the pro-survival function of Bcl-2, Bcl-XL, and Bcl-w and induces apoptosis in a variety of cancer cell types including leukemias." (PMID 23431463, 2013). "Re-introduction of p16INK4A sensitizes leukemia cells to mitochondrial cell death by changing the balance of pro- and anti-apoptotic BCL2 proteins at the mitochondria." (PMID 23828551, 2013). "We show for the first time that maintenance of Bcl-2 expression is critical for HoxA9-dependent immortalization and influences the latency of HoxA9-dependent leukemia." (PMID 24177192, 2013). "A good example is miR-15a, one of the most down-regulated microRNAs in MLL-FP leukemias, which has been known to target the antiapoptotic gene BCL2." (PMID 24213472, 2012). "For this purpose we first selected ABT-737, a BH3 mimetic, shown to inhibit the pro-survival function of Bcl-2, Bcl-xL and Bcl-w and to induce apoptosis in a variety of cancer cell types including leukemias." (PMID 22479469, 2012). "BCL2 is overexpressed in almost all types and subtypes of leukemia, indicating the importance of this molecule in disease pathogenesis and evolution." (PMID 21941553, 2012). "KIF11 inhibition has also been reported to kill human ovarian carcinoma and leukemia cells via the intrinsic apoptotic pathway in a Bcl-2-sensitive manner." (PMID 23071517, 2012). "An in vitro study has demonstrated that the presence of adipocytes protects leukemia cells from chemotherapeutic agents through Bcl-2 overexpression." (PMID 21991326, 2011). "Anti-apoptotic Bcl-2 contributes to the survival and chemoresistance of quiescent leukemia CD34+ cells." (PMID 21595920, 2011). "The anti-apoptotic proteins Bcl-2 and Bcl-xl also contribute to the survival and chemoresistance of quiescent leukemia CD34+ cells." (PMID 21595920, 2011). "The toad skin secretion bufalin was found to induce apoptosis in human-leukemia cells by altering expression of apoptotic genes c-myc and bcl-2." (PMID 19674474, 2009). "We conclude that the diatoms contained water-soluble compounds able to induce various types of cell death in leukaemia cells, including classic apoptotic and autophagic death, both via pathways blocked by Bcl-2 and pathways overriding Bcl-2." (PMID 20098602, 2009).
leukemia (continued). "A subclone of the IPC leukemia cells expressing the prosurvival oncogenic protein Bcl-2 is resistant towards several apoptotic stimuli, including current anti-leukemic chemotherapy drugs like the anthracycline." (PMID 20098602, 2009). "When compared to HA14-1, which is a SMI to Bcl-2 used against leukemia cell lines HL60 and K562, ApoG2 has a IC50 which is 200-fold lower." (PMID 18275607, 2008). "In the present study, we found that the expressions of both survivin and Bcl-2 were downregulated concurrently in ponicidin induced apoptosis on the two leukemia cell lines." (PMID 19330074, 2008). "Though Bax expression remained constant before and after apoptosis ocurred, the ratio of Bcl-2 to Bax was downregulated, apoptosis therefore was induced in ponicidin treated leukemia cells." (PMID 19330074, 2008). "In this study, our results revealed that Bcl-2 expression was down-regulated remarkably in ponicidin induced apoptosis on leukemia cells." (PMID 19330074, 2008). "Groups of TRAF2DN/Bcl-2 mice that had developed leukemia were injected i.v. with empty liposomes or with liposomes containing either CDDO (20 mg/Kg) or CDDO-Im, at doses of 5, 10 or 20 mg/kg/day." (PMID 17593960, 2007). "For these studies, we used TRAF2DN/Bcl-2 mice that have developed leukemia, as indicated by the presence of a majority of CLL (FSCM B220M) cells in blood (over 4×106 B cells/ml)." (PMID 17593960, 2007). "For example, transfection-mediated overexpression of Bcl-2 rendered Jurkat leukaemia cells refractory to killing by a cytotoxic T-cell clone." (PMID 17311012, 2007). "Taxol was included as a reference since it has been shown to induce Bcl-2 phosphorylation in human leukaemias and solid tumour cells." (PMID 11857026, 2002). "For example, the pan‐HDACi SAHA (vorinostat) potentiated the therapeutic efficacy of the dual BCL‐2/BCL‐xL inhibitor ABT‐737 (a predecessor to venetoclax) to human leukemia and myeloma cells, partially through the upregulation of the pro‐death BCL‐2 protein BIM." (PMID 40370107, 2025). "While Jurkat cells are commonly used in leukemia research, the efficacy and specificity of PZ703b in modulating Bcl-2 and Bcl-xL levels may vary across different cell types and are independent of HIV infection." (PMID 40141414, 2025). "As a potent oral Bcl-2 inhibitor, Ven has excellent antitumor effects on various leukemias." (PMID 41220934, 2025). "For example, IL-6 is known to activate STAT3, a key transcription factor in leukemia, leading to the promotion of survival pathways, anti-apoptotic proteins (e.g., BCL-2), and pro-angiogenic factors, all of which contribute to the persistence of leukemia cells in the bone marrow." (PMID 40486651, 2025). "In the cells cultured in vitro, the synergistic use of HHT and BTZ enhanced the cytotoxicity of BTZ against K562 leukemia cells, reduced the expression of the anti-apoptotic proteins Bcl-2 and Mcl-1, while enhancing the expression of the pro-apoptotic protein Bax." (PMID 39949739, 2025). "In leukemia cell lines such as K-562 and HL-60, elevated Bcl-2 expression has been repeatedly documented in the literature and associated with chemoresistance, which may also explain the lack of response observed in our study." (PMID 41375095, 2025). "In leukemia cells, this activation can have pro- or anti-survival consequences, and has been shown to induce apoptosis by suppressing the expression of survival genes such as Bcl2 and survivin." (PMID 40805157, 2025). "Next, we assessed whether co-targeting of MCL-1 and BCL-2 would re-sensitize VEN-insensitive leukemia cells and investigated cell death induction by titrating concentrations of VEN, S63845, or their combination." (PMID 38961053, 2024). "Regulating the expression of Bcl-2 and Bcl-xL could improve leukemia therapy and ameliorate human health." (PMID 38611876, 2024).
leukemia (continued). "We selected three genes that are targeted by FDA-approved inhibitors for treatment of leukemia: Bcl2 (inhibited by Venetoclax), Btk (Ibrutinib), and Kit (Imatinib) and plotted the calculated TPM values for each TT-seq replicate after DMSO and I-BRD9 treatment, connected by arrows." (PMID 38126767, 2024). "Furthermore, a murine leukemia model with conditional expression of BCL-2 demonstrated that leukemic cells depend on BCL-2 for survival and growth." (PMID 38424137, 2024). "Furthermore, the synergistic inhibition of leukemia burden by combining a Bcl-2 inhibitor and ruxolitinib was demonstrated in a murine model in separate research." (PMID 38273387, 2024). "Furthermore, Bcl-2 inhibition hampers ATP production in leukemia stem cells (LSCs) by hindering oxidative phosphorylation." (PMID 38994204, 2024). "Increased expression of Bcl-2 and Bcl-xL is observed in some leukemias." (PMID 38611876, 2024). "Moreover, in a zebrafish model of human Notch1-induced T-ALL, stable overexpression of Bcl-2 dramatically facilitates Notch1-mediated leukemia onset, indicating the synergy between the Notch pathway and the Bcl-2-mediated anti-apoptotic pathway." (PMID 39684550, 2024). "Further, we addressed anti-leukemia activity of combined BCL-2 and OxPhos inhibition in a series of PDX BCP-ALL samples characterized by different VEN-sensitivities titrating a dose-response matrix with combinations of increasing concentrations of VEN or Oligomycin." (PMID 38961053, 2024). "Upon early-phase rituximab treatment, Bcl-2 family proteins are downregulated in leukemia cell lines due to preferential killing of CD20 + cells, causing decreased IL-10 production, inhibited STAT3 activation, and reduced interaction with the Bcl-2 promoter." (PMID 39501277, 2024). "For example, CD20/CD44 dual targeted siRNA delivery using layer-by-layer NPs (LbL NPs, PLGA/PLA/siRNA/PLA; PLGA, poly-(D,L-lactide-co-glycolide); PLA, poly-l-arginine) with BCL-2 siRNA in B cell lymphoma and leukemia cells downregulated BCL-2, induced apoptosis, and reduced the blood cancer cells." (PMID 36678782, 2023). "To further study the mechanistic background of the VEN + PERI-induced synergistic apoptosis induction, we performed NGS-based custom panel RNA sequencing of 208 genes related to the PI3K/AKT and BCL-2 pathways as well as other apoptosis and leukemia signaling cascades." (PMID 36674872, 2023). "Additionally, this analogue was also shown to enhance Bcl-2-mediated antiapoptosis in leukemia cells." (PMID 36982637, 2023). "Next, the researchers showed that knockdown of circSPI1 inhibited cell proliferation, induced partial myeloid differentiation, and enhanced apoptosis of leukemia cells through upregulation of the levels of expression of apoptosis-related proteins such as Bcl-2, CDK6, p-ERK1/2." (PMID 37124518, 2023). "Additionally, metformin and phenformin are also potentiators of the cytotoxicity of Bcl2 antagonist - ABT-737 against leukemia." (PMID 37842232, 2023). "In addition, statistically significant inhibition of anti‐apoptotic BCL‐2 protein by HB 0.2 and 0.4 mg·mL−1 treatments was confirmed in UT‐7 leukemia only." (PMID 36369656, 2023). "However, the treatment only marginally affected Bcl-2 and Bcl-xL levels in the leukemia cells, and even upregulated the anti-apoptotic protein Mcl-1 especially in Ba/F3-ITD mutant and Ba/F3-FLT3-WT cell lines." (PMID 36865133, 2023). "In terms of the codominant model, individuals with the AA genotype of the Bcl-2 gene had a greater vulnerability to leukemia with an odds ratio (OR) of 3.17 (95% confidence interval (CI): 1.33–7.53), a relative risk (RR) of 1.88 (95% CI: 1.09–3.25), with a significant p-value (<0.009)." (PMID 37232720, 2023). "Furthermore, VEGFR3 overexpression or activation has been proven to confer chemoresistance in others types of cancer such as leukemia by enhancing Bcl-2 expression." (PMID 36835014, 2023).